PCNA (proliferating cell nuclear antigen)
Diseases named in the same sentence as PCNA in open-access papers (continued):
Sharing a sentence is not in itself a finding about the gene and the disease.
leiomyoma (14 papers, 2008 to 2023). A well-circumscribed benign smooth muscle neoplasm characterized by the presence of spindle cells with cigar-shaped nuclei, interlacing fascicles, and a whorled pattern. "Leiomyoma cocultured with adipocytes and leptin treatment significantly increased in expression of PCNA and TNF-α." (PMID 36771423, 2023). "Adipocyte coculture and leptin treatment has previously been shown to increase PCNA expression in leiomyoma cells." (PMID 36771423, 2023). "The suppressed PCNA expression and activated caspase‐3 confirm its antiproliferative and pro‐apoptotic effects on leiomyoma stem cells." (PMID 35118811, 2022). "On top of that, treatment with SB also reduces the expression of PCNA, cyclin E, and cdc2 in hCG-treated leiomyoma cells." (PMID 35800452, 2022). "Our study, through the assessment of two independent parameters, namely PCNA and Ki67 index, confirms reduction in proliferation in leiomyomas after UPA treatment." (PMID 33546154, 2021). "In a previous study, immunohistochemical (IHC) staining revealed a decreased PCNA expression in Eker rat leiomyomas treated with 1, 25-dihydroxyvitamin D3, as compared to vehicle-treated control rats." (PMID 31013842, 2019). "Knockdown of EGR2 in leiomyoma cells increased myc and PCNA expression as well as collagen deposition." (PMID 28687085, 2017). "Proliferation markers such as Ki67 and proliferating cell nuclear antigen (PCNA) are highest in leiomyoma in the luteal/secretory phase." (PMID 22272226, 2012). "E2 exposure is a well-recognized risk factor for cancer of the breast and endometrium, and E2 enhances PCNA gene expression in human myometrial and leiomyoma tissues as well." (PMID 18949048, 2008). "Indeed, IGF-I has been shown to increase significantly the expression of immunoreactive PCNA and to stimulate cell proliferation in cultured leiomyoma cells compared to untreated controls." (PMID 28930160, 2017). "We sought to investigate the effect of STAT3, ERK, and AKT inhibitors in PCNA and TNF-α expression in leiomyoma cells cocultured with adipocytes and leptin treatment." (PMID 36771423, 2023). "Studies demonstrated that progesterone signaling promotes the growth and proliferation of fibroid cells through increasing proliferating cell nuclear antigen (PCNA) expression, which increases both the number of fibroid cells and the size of fibroid tumors." (PMID 37190026, 2023). "Lower concentrations (≤1 μg/mL) stimulated proliferation, whereas higher concentrations (≥10 μg/mL) significantly inhibited proliferation, decreased proliferating cell nuclear antigen (PCNA), and increased apoptosis of both myometrial and leiomyoma cells." (PMID 33918317, 2021). "The respective inhibitors reduced the levels of pSTAT, pERK1/2, and pAKT and suppressed the intracellular staining intensity of PCNA, TNF-α, TGF-β3, and VEGF-A, in addition to reversing the effect of leptin treatment and adipocyte coculture on leiomyoma cell growth." (PMID 36771423, 2023). "Finally, STAT3, ERK, and AKT inhibitor treatment suppressed PCNA, TNF-α, TGF-β3, and VEGF-A intracellular staining intensity in both adipocyte coculture and leptin treated leiomyoma cells." (PMID 36771423, 2023). "Moreover, higher proliferative activity, evidenced by proliferating cell nuclear antigen (PCNA) and the mitotic index, was encountered in leiomyomas during the luteal (secretory) phase compared to the proliferative phase." (PMID 33291422, 2020). "Moreover, higher proliferative activity, demonstrated by proliferating cell nuclear antigen (PCNA) and the mitotic index, was observed in leiomyomas during the luteal (secretory) phase." (PMID 27466209, 2016). "Furthermore, it has been shown that leiomyoma cells and normal myometrial cells treated with PDGF show upregulated expression of collagen I, as well as PCNA." (PMID 20537183, 2010).
leiomyoma (continued). "Supporting the idea that hCG may exert a direct effect over the growth of uterine leiomyomas by regulating cell cycle control mechanisms, the expressions of proliferating cell nuclear antigen (PCNA), cyclin E and cdc2 were all significantly increased in leiomyoma cells upon hCG treatment." (PMID 28930160, 2017).
lymphoma (14 papers, 1992 to 2025). A malignant (clonal) proliferation of B- lymphocytes or T- lymphocytes which involves the lymph nodes, bone marrow and/or extranodal sites. "Proliferating cell nuclear antigen (PCNA), an auxiliary protein of DNA polymerase and highly expressed during the cell cycle, is expressed in proliferating macrophages within populations of TAMs and is a proliferation-associated marker of human lymphoma-associated macrophages." (PMID 32196489, 2020). "Losartan, an antagonist of AT1R, reduced lymphoma volume and size in nude mice, and the proliferation and viability and the PCNA and Ki67 levels of SNK-6 cells." (PMID 32969473, 2020). "Ang II increased the lymphoma volume and size in nude mice, the proliferation and viability and the proliferating cell nuclear antigen (PCNA) and Ki67 levels of SNK-6 cells." (PMID 32969473, 2020). "In another study, in vitro treatment of lymphoma cells with T3 and T4 activated proliferation, as indicated by increased expressions of PCNA, as well as cyclins D, A2, and B." (PMID 30814976, 2019). "Others also found high levels of PCNA positivity in DLBCLs and similar levels of TK-1 activity in low- and high-grade lymphoma." (PMID 24397937, 2014). "In one study, PCNA activity was markedly increased in the higher grade lymphoma group compared to that in the low grade lymphoma and orbital pseudotumor group." (PMID 20379424, 2008). "Lymphomas where > 50% of cells showed positive staining for PCNA had inferior 5-year survival as compared with those with less than 50% of positive cells (57% vs 41%, P = 0.008)." (PMID 1358164, 1992). "Many prognostic factors have been reported in dogs with lymphoma, such as tumor stage and substage, immunophenotype, hypercalcemia, anemia, thrombocytopenia, histopathology grade, mitotic index, anatomic location, proliferating cell nuclear antigen, aneuploidy, and proliferation indices." (PMID 40003004, 2025). "Given these limitations associated with standard CsPt treatment and the high sensitivity of DDTD lymphoma to low concentrations of CsPt in vitro, we predicted that tumor-specific defects in PCNA ubiquitination could actually chemosensitize those tumors to lower doses of CsPt in vivo." (PMID 29721165, 2018). "Lymphomas with both a large percentage (> 50%) of PCNA positive cells and a larger than the median SPF had inferior outcome as compared with lymphomas where either one or both of these factors were small." (PMID 1358164, 1992).
sarcoma (13 papers, 2012 to 2025). A usually aggressive malignant neoplasm of the soft tissue or bone. "ISG15 and IF16 are directly linked together but through PCNA and then through CCND1 they connect indirectly to the common to all sarcomas’ major hubs FGF2 and IL-6." (PMID 34359782, 2021). "Expression of other checkpoint molecules such as T-cell immunoglobulin and mucin domain-3 (TIM-3) ligands and NKp44-inhibiting proliferating cell nuclear antigen (PCNA) was also reported in sarcomas." (PMID 33322371, 2020). "Consistent with the analysis of the fresh sarcoma explants, the in vitro propagated primary sarcoma explants robustly expressed a similar but enhanced signature including the markers PCNA, CD112, CD155 to a lesser extent and HLA-ABC (n = 32)." (PMID 32082316, 2020). "To investigate the anti-proliferative activity of DVDMS-mediated SDT on sarcoma tumors in vivo, we directly analyzed the expression of PCNA protein by immunohistochemistry." (PMID 26631871, 2015). "Immunostaining for CD3 and PCNA was performed at weeks 16, 20–24 and 30 using lymph node tissue and human undifferentiated sarcoma tissue with high mitotic activity as respective positive controls." (PMID 24670925, 2014). "PCNA showed 99% positive area in all sarcomas, congruent with the highly aggressive nature of this tumor type." (PMID 23164239, 2012). "Additionally, we found that CNN3 mRNA expression had a significant positive correlation with the mRNA expression of two mesenchymal markers, Snail and vimentin (VIM), and two tumor proliferation markers, MKI67 and PCNA, in sarcoma." (PMID 32667904, 2020). "Analysis of tumors from 32 sarcoma patients identified the proliferative marker PCNA and DNAM-1 ligands CD112 and/or CD155 as commonly expressed antigens that could be efficiently targeted by genetically modified (GM) NK cells." (PMID 32082316, 2020). "Freshly isolated primary sarcomas expressed activating ligands CD112 and low levels of CD155 and CD48 as well as the inhibitory ligands PCNA, MUC1, HLA-ABC, and HLA-DR/DP/DQ (n = 13)." (PMID 32082316, 2020). "Amongst the eight remaining hub genes, CDC20, CCNB2, AURKB, MAD2L1, CENPE, KIF2C, and PCNA were highly expressed and related with negative prognosis of sarcoma." (PMID 31870357, 2019). "Interestingly, we demonstrated that the PCNA index revealed a high positive correlation (r = 0.8247, p < 0.001) with histologic grading of sarcomas grown on the CAM, as opposed to Ki-67 where the expression was <20% in both groups of tumors." (PMID 28651614, 2017).
prostatic hyperplasia (12 papers, 2012 to 2025). "Results showed increased BW and prostate weight, elevated serum testosterone and DHT levels, prostatic hyperplasia, and overexpression of PCNA, iNOS, and COX-2 in F344 rats with induced prostatic hyperplasia." (PMID 31941927, 2020). "PCNA has been shown to be directly correlated with the proliferative state of various tissues, and so, correlates with the development of prostate diseases." (PMID 30322186, 2018). "In conclusion, YJT significantly reduced prostate weights, prostatic hyperplasia, PCNA expression, and DHT levels in the serum and prostates of experimental rats." (PMID 22520510, 2012). "This study further confirmed that a daily administration of 10–270 μg/kg BPA in adult rats could induce prostatic hyperplasia, which is characterized by the increased organ coefficient of prostate, PCNA expression and the ratio of proliferation/apoptosis." (PMID 32753632, 2020). "Results revealed that low-dose BPA induced prostatic hyperplasia with increased PCNA/TUNEL ratio." (PMID 32753632, 2020). "Our findings indicate that PFE significantly inhibited the development of BPH; decreased the relative prostate weight, the level of testosterone and DHT in serum and prostatic tissue, prostatic hyperplasia, expression of PCNA, and increased the antioxidant enzymes." (PMID 28774334, 2017). "In the present study, YJT significantly decreased PCNA expression in the prostate compared with the BPH group, in parallel with a reduction in the prostatic hyperplasia." (PMID 22520510, 2012). "However, oral administration of LCW markedly inhibited the mRNA expression of PCNA compared to the TPH group, suggesting suppression of prostatic hyperplasia." (PMID 30724641, 2019).
endometrial cancer (11 papers, 2012 to 2025). Primary or metastatic malignant neoplasm involving the endometrium (mucous membrane that lines the endometrial cavity). "Here, we propose a potential new strategy for controlling the interaction between POLD1 and PCNA through the splicing factor SNRPB in endometrial cancer cells." (PMID 39910288, 2025). "Next, we analyzed the relationship between RCOR2 and the proliferation-related genes MKI67, CCND1, and PCNA under the mRNA levels, in endometrial cancer." (PMID 40936699, 2025). "PCNA is a nuclear protein, which is expressed in proliferating cells during the S phase of the cell cycle, as a useful tool in mammary, cervical, and endometrial cancer prognosis research." (PMID 31219800, 2019). "PCNA is usually used as a biochemical marker for evaluating the proliferation of endometrial cancer cells, and C3 is one of the estrogen-responsive genes." (PMID 29849935, 2018). "Previous study had verified that the HERVWE1 expression was synchronous with the PCNA expression in endometrial carcinoma tissue." (PMID 22457770, 2012). "To determine whether miR-204-5p expression affects the in vivo proliferative ability of endometrial carcinoma cells, we examined the expression of two proliferation protein markers ki67 and PCNA by immunohistochemical staining (last two pairs of panels)." (PMID 24321270, 2013). "We found that endometrial carcinoma cells could increase the PCNA expression in T cells." (PMID 36756714, 2023). "Furthermore, WB showed that RCOR2 knockdown or overexpression could change the expression of MKI67, CCND1, and PCNA in endometrial cancer cells remarkedly, which further demonstrated at the protein level that RCOR2 the proliferation of endometrial cancer cells." (PMID 40936699, 2025). "Correlation analysis showed that all three genes, MKI67, CCND1, and PCNA, exhibited a significant positive correlation with RCOR2 mRNA expression in endometrial cancer tissues." (PMID 40936699, 2025). "Moreover, the qPCR results of proliferation-related genes, MKI67, CCND1, and PCNA, supported the regulatory effects of ROCR2 on endometrial cancer cell proliferation." (PMID 40936699, 2025).
leukemia (11 papers, 2009 to 2025). A malignant (clonal) hematologic disorder, involving hematopoietic stem cells and characterized by the presence of primitive or atypical myeloid or lymphoid cells in the bone marrow and the blood. "Hematoxylin and eosin (H&E) and immunohistochemical staining of proliferating cell nuclear antigen (PCNA) further demonstrated that deficiency of Fto instead of Alkbh5 restrained leukemia cells infiltration and proliferation." (PMID 40435251, 2025). "Immunohistochemical (IHC) staining confirmed that SHQ1 deficiency significantly decreased human CD45+ leukemia burden and cell proliferation (reflected by proliferating cell nuclear antigen (PCNA) staining) in the spleen." (PMID 30323192, 2018). "Naringenin has been found to suppress the rate of PCNA expression in leukemia cell line HL-60, thereby indicating its anti-proliferative activity." (PMID 33339267, 2020). "Cytoplasmic proliferating cell nuclear antigen (PCNA) is highly expressed in acute myeloid leukemia (AML) cells, supporting oxidative metabolism and leukemia stem cell (LSC) growth." (PMID 39732733, 2024). "PCNA and MCM2 levels had a downward trend in xenograft leukemia from sample B-01-Dx." (PMID 33722259, 2021). "Xenograft mice inoculated with HL-60 leukemia cells demonstrated that the intraperitoneal administration of 2′-HCA inhibited tumor growth by increasing of TUNEL staining, the expression levels of nitrotyrosine and pro-apoptotic proteins, but reducing of PCNA protein expression." (PMID 34834209, 2021).
Hyperglycemia (10 papers, 2016 to 2025). An increased concentration of glucose in the blood. "The increase in PCNA expression observed in QHL-treated groups suggests that QHL has a mitigating effect on the inhibitory influence of hyperglycemia." (PMID 39954213, 2025). "RES treatment increased hyperglycemia-impaired endothelial cell proliferation, which showed an increased number of PCNA-positive endothelial cells compared with db/db mice." (PMID 31068817, 2019). "Pim-1 and proliferating cell nuclear antigen (PCNA) expression levels in arterial samples from streptozotocin-induced hyperglycemia rats were increased, compared with their weak expression in normoglycemic groups." (PMID 29179437, 2017). "Considering these results, it might be relevant to suggest that PCNA-related DNA methylation might be one of the possible pathways in the dysregulation of DNA methylation in induced hyperglycemia during spermatogenesis." (PMID 38164482, 2024). "Our data are comparable to these previous observations; specifically, in the current work, SMC-specific OGT deletion reduced SRF expression concomitant to attenuated PCNA expression in the aortic vasculature of smOGTKOApoE-/- following Western diet-induced hyperglycemia." (PMID 37175604, 2023). "Notably, while STZ-induced hyperglycemia augmented cell proliferation marker PCNA expression in ApoE−/− mice (3.6-fold vs. Control), CrP administration significantly inhibited PCNA expression (80% vs. STZ)." (PMID 28345659, 2017). "STZ-induced hyperglycemia increased α-SMA (1.6-fold) and PCNA staining (2.0-fold) in ApoE−/− mice, indicating enhanced smooth muscle cell content and cell proliferation." (PMID 28345659, 2017). "This reduction in PCNA expression is consistent with the well-documented negative impact of hyperglycemia on MSC proliferation, as high-glucose environments are known to induce cellular stress, impair metabolic activity, and reduce mitotic capacity." (PMID 39954213, 2025). "Given that chronic hyperglycemia has been shown to impair neurogenesis in zebrafish, we decided to analyze neural stem cell (NSC) proliferation in key neurogenic niches by performing PCNA immunostaining." (PMID 35359845, 2022). "Attenuated lesion progression was accompanied with inhibition of hyperglycemia-induced TSP-1 expression and reduced protein O-glycosylation following CrP treatment; also, PCNA and vimentin (SMC synthetic marker) expression were reduced while SM-MHC (SMC contractile marker) levels were increased." (PMID 28345659, 2017). "Although the expression of PCNA in IPCs was not as strong as in undifferentiated hMSCs, it seemed to have contributed to the efficiency of IPCs in controlling hyperglycemia in vivo." (PMID 26756576, 2016).
atherosclerosis (9 papers, 2012 to 2022). A disease characterized by the build-up of fatty material and calcium deposition in the arterial wall resulting in partial or complete occlusion of the arterial lumen. "We found a significant reduction in proliferation-related protein (α-SMA and PCNA) expression in the aortic of atherosclerosis mice treated with Pae compared with the HFD group." (PMID 36034838, 2022). "In the Atherosclerosis + Vector group, the mRNA and protein expressions of NF-κBp65, PCNA, p-p38 MAPK, p-JNK, and p-ERK1/2 were significantly increased, as compared with the control group." (PMID 31781638, 2019). "Further data demonstrate a marked and dose-dependent reduction in neointimal expression of PCNA after fed with HLP in HFD-treated rabbits, indicating that HLP ameliorates atherosclerosis by reducing PCNA expression, both in vitro and in vivo." (PMID 31817413, 2019). "CD4+ and CD8+ T cells as well as PCNA+ cells are cellular markers of inflammatory responses and active proliferative activity in atherosclerosis." (PMID 22238605, 2012). "Our study showed a significant and dose-dependent decrease in neointimal expression of PCNA after treatment with acarbose (2.5 and 5.0 mg kg−1) in HCD-fed rabbits, indicating that acarbose ameliorates atherosclerosis by reducing PCNA expression." (PMID 27924924, 2016). "Significant increases in intimal areas, PCNA‐ and F4/80‐ positive cells in the carotid artery indicates that HU contributes to atherosclerosis, though no plague were found." (PMID 30690853, 2019). "In this study, we demonstrated that Kiom-18, a novel composition of C. cassia, P. densiflora, C. longa and G. glabra, prevents atherosclerosis through the anti-proliferative effect on VSMCs via the regulation of cell cycle-related proteins such as CDK2, CDK4, cyclin D1, cyclin E1, Rb, and PCNA." (PMID 27465365, 2016). "Compared with the Atherosclerosis + Vector group, the mRNA and protein expressions of NF-κBp65, PCNA, p-p38 MAPK, p-JNK, and p-ERK1/2 were significantly decreased in the Atherosclerosis + Knockdown group and increased in the Atherosclerosis + Overexpression group." (PMID 31781638, 2019).